MTOR (mechanistic target of rapamycin kinase)
Diseases named in the same sentence as MTOR in open-access papers (continued):
Sharing a sentence is not in itself a finding about the gene and the disease.
endometrial cancer (continued). "Gene mutations in PIK3CA, PIK3R1, KRAS, PTEN, and PPP2R1A commonly detected in type I endometrial cancer lead to PI3K/Akt/mTOR pathway activation." (PMID 34831139, 2021). "We found that PQR309, a dual PI3K/mTOR inhibitor, reduces proliferation in endometrial cancer cells and endometrial cancer stem cells by decreasing CDK6 and increasing p27 and subsequently inducing G1-phase arrest." (PMID 34831139, 2021). "As in other studies, in this paper, we identified sulforaphane as a potent inhibitor of PI3K/AKT/mTOR pathway signaling in endometrial cancer." (PMID 32443471, 2020). "This is consistent with the sulforaphane mediated inhibition of PI3K/AKT/mTOR contributing to apoptosis in endometrial cancer cells." (PMID 32443471, 2020). "Recently studies have suggested that aberrant activation of the Notch signaling accelerates cell proliferation in endometrial cancer, and suppression of mTOR signaling pathway in EC inhibits tumor initiation and progression." (PMID 32239181, 2020). "In summary, our study revealed that the PI3K/AKT/mTOR pathway and tumor angiogenesis molecules contribute to the pathogenesis of endometrial cancer." (PMID 32908897, 2020). "Treatment of these cells with mTOR inhibitors reversed endometrial cancer cell proliferation, migration, and epithelial–mesenchymal transition (EMT) marker expression." (PMID 32899752, 2020). "Accordingly, several groups have recently reported the activity of multiple PI3KCA and mTOR inhibitors in endometrial cancer in preclinical studies." (PMID 31934607, 2020). "TAMs promote epithelial mesenchymal transition via activating the PI3K/AKT/mTOR signalling pathway in endometrial cancer." (PMID 32226513, 2020). "Generally speaking, all of our results demonstrated that STYX/FBXW7 axis participates in the development of endometrial cancer cell via Notch–mTOR signaling pathway." (PMID 32239181, 2020). "Our imperfect understanding of the interplay of YB-1 and mTOR is even more pronounced in endometrial cancer." (PMID 31947591, 2020). "Clinical trials of therapies that target specific molecular abnormalities for endometrial cancer, such as mTOR inhibitors and vascular epidermal growth factor (VEGF) inhibitors, have shown some promise in the second-line setting." (PMID 32443471, 2020). "AKT and mTOR inhibitors reduced endometrial cancer cell line viability and prevented further reduction by sulforaphane." (PMID 32443471, 2020). "In endometrial cancer, METTL14 mutation or METTL3 down-regulation leads to a decrease of mTOR m6A levels, which is a regulator of oncogene AKT." (PMID 32998774, 2020). "PIK3CA was identified as one of the most commonly mutated “driver genes” in endometrial tumors and, accordingly, multiple PI3KCA, AKT and mTOR targeted inhibitors are currently in Phase I-III clinical trials against solid tumors including endometrial cancer." (PMID 31934607, 2020). "The activation of mTOR leads to an increase in KIF5B expression in the cell line Ishikawa (endometrial cancer), which, in turn, leads to EMT." (PMID 33114763, 2020). "Using immunohistochemistry and Western blotting, they observed that obese women with endometrial cancer showed estrogen (ERα-dependent)-induced FTO nuclear accumulation in the mTOR signaling pathway, which contributed to worse clinical outcomes." (PMID 31947591, 2020). "mTOR activation via CCL18 leads to cell migration in tumors such as endometrial cancer, ovarian cancer, and oral squamous cell carcinoma." (PMID 33114763, 2020). "Based on its role in cancer progression, various inhibitors of PI3K/AKT/mTOR are currently being evaluated in clinical trials for treating patients with metastatic, recurrent, and persistent endometrial cancer." (PMID 32443471, 2020).
endometrial cancer (continued). "Enhanced activity of the mTORC1 pathway is well documented in few human cancers, although limited studies discuss the regulation of the mTOR pathway in endometrial cancer." (PMID 32899752, 2020). "In recent years, the oncogenic effects of phosphatidylinositol 3-kinase (PI3K)/Akt/mammalian target of rapamycin (mTOR) signaling in cancer, including in endometrial carcinoma, have received increasing recognition." (PMID 32984001, 2020). "Upregulation of CD47 promoted progression of endometrial carcinoma by activating PI3K/Akt/mTOR signaling pathway." (PMID 32984001, 2020). "CD47 upregulation contributes to the activation of PI3K/Akt/mTOR signaling pathway in endometrial carcinoma cells." (PMID 32984001, 2020). "A new bidirectional inhibitor of PI3K and mTOR is more effective than a simple inhibitor of mTOR (rapamycin) in inhibiting endometrial cancer." (PMID 31440472, 2019). "The underlying mechanisms of RAD001 treatment is based on the inhibition of AKT and mTOR phosphorylation, associated to up-regulation of LC3II protein in Ishikawa (IK) and HEC-1A endometrial cancer cells lines." (PMID 31850214, 2019). "This knowledge about autophagy activation by mTOR inhibitors and immune system participation is a novel promising direction for endometrial cancer therapies." (PMID 31850214, 2019). "PTEN is an essential tumor suppressor gene that antagonizes the PI3K/Akt/mTOR antiapoptotic pathway and is often abnormal in endometrial cancers." (PMID 30765787, 2019). "P13K/mTOR pathway inhibitors can sensitize endometrial cancer to radiation therapy by inhibiting HIF-1a/VEGF signaling." (PMID 30935077, 2019). "Hedgehog signaling pathway inhibitors have been shown to successfully impair proliferation of endometrial cancer cells, and mTOR inhibitors have also been investigated for their therapeutic potential in endometrial cancers." (PMID 31850214, 2019). "Adiponectin can not only inhibit the proliferation and migration of endometrial cancer cells through the AMPK/mTOR/S6K1 signaling pathway but can also enhance the sensitivity of endometrial cancer cells to insulin through the AMPK/S6K1/IRS1 signaling pathway." (PMID 31440472, 2019). "Alterations in PI3K/AKT/mTOR signaling pathway are very common in endometrial carcinoma and its precursor lesions." (PMID 30886832, 2019). "mTOR inhibitors evaluated in endometrial cancer include ridaforolimus, everolimus, and temsirolimus." (PMID 28184290, 2017). "Although metformin has been noted to act through alteration of AMPK/mTOR, K-Ras, and the eIF4E-binding protein in diabetic patients and cancer cells, the precise mechanisms for its inhibition of endometrial cancer are not yet fully understood." (PMID 28114390, 2017). "To test if pharmacological suppression of mTOR signaling will suppress the growth of endometrial cancer, we treated cells of an endometrial line, Ishikawa, with two FDA-approved mTOR inhibitors (Everolimus and BEZ235)." (PMID 27980219, 2017). "Collectively, these findings showed that suppression of mTOR signaling decreased viability and proliferation of endometrial cancer cells." (PMID 27980219, 2017). "Although metformin has been found to inhibit PI3K/AKT/mTOR and K-Ras signaling in endometrial cancer, the precise mechanism of the drug’s action against the disease has not been fully delineated." (PMID 28114390, 2017). "This cellular reprogramming of glucose metabolism to fuel tumor cell growth is largely thought to be driven by the AKTphosphoinositide 3-kinase (PI3K)/mammalian target of rapamycin (mTOR) pathway, which is commonly activated in endometrial carcinomas." (PMID 29214032, 2017). "Metformin, an antidiabetic drug, is effective for endometrial cancer through inhibition of the PI3K-Akt-mTOR pathway by activating LKB1-AMPK and reduction of insulin and insulin-like growth factor-1 due to AMPK activation." (PMID 25734181, 2015).
endometrial cancer (continued). "When endometrial cancer somatic mutation landscape (COSMIC database) was aligned to the risk modifiers identified in the present study, MTOR was the first common gene ranking 130th among somatic mutations." (PMID 26517685, 2015). "mTOR inhibition with temsirolimus has encouraging single-agent activity in endometrial cancer which has been shown to be more effective in chemotherapy-naive patients than in chemotherapy-treated patients and is independent of PTEN status." (PMID 25760378, 2015). "In our clinical experience, letrozole alone is already able to modulate the mTOR axis in breast cancer suggesting its use also in other endocrine-related cancer such as estrogen receptors positive endometrial cancer." (PMID 26244161, 2015). "Another mTOR inhibitor, ridaforolimus, has antitumor activity and acceptable tolerability in advanced endometrial cancer patients." (PMID 25760378, 2015). "Alterations in the mTOR pathway, including inactivating PTEN mutations and PIK3CA amplifications or activating mutations, are common in endometrial cancers 14,15." (PMID 25417601, 2015). "Similar to the other preoperative window studies in breast and endometrial cancer 18,40, we found that metformin significantly decreased phosphorylation of downstream targets of the mTOR pathway, including p-Akt, p-S6, and p-4E-BP-1." (PMID 25417601, 2015). "Based on the biological rationale of targeting the mTOR pathway, mTOR inhibitors as single agent have entered clinical trials in endometrial cancer." (PMID 24526917, 2014). "Other agents that can affect the PI3K/PTEN/Akt/mTOR signaling pathway have been developed and are currently under investigation in women with endometrial cancer." (PMID 24526917, 2014). "In a recent abstract report on 42 patients with recurrent endometrial cancer, the effects of concomitant letrozole and the mTOR inhibitor everolimus were studied." (PMID 24498853, 2014). "PTEN mutations and methylation are common in type I endometrial cancer, which suggests the potential value of treatment with an mTOR inhibitor that blocks the PI3K-AKT-mTOR pathway." (PMID 23291663, 2013). "Over 40% of type I endometrial cancers have a loss of PTEN and an activation of the PI3K/AKT/mTOR pathway." (PMID 23864861, 2013). "In a phase II study of everolimus, the first oral mTOR inhibitor for endometrial cancer, SD for at least 8 weeks was found in 43% of patients." (PMID 23291663, 2013). "Several studies reported increased expression of mTOR protein and its phosphorylated form (p-mTOR) in endometrial cancer tissues and cell lines." (PMID 22920721, 2012). "In summary, our data show that thioridazine can inhibit the PI3K/Akt/mTOR/p70S6K signaling pathway and exert cytotoxic effect on cervical and endometrial cancer cells by inducing cell cycle arrest and apoptosis." (PMID 22460505, 2012). "The PI3K (phosphatidylinositol-3-kinase)/mTOR (mammalian target of rapamycin) pathway is frequently activated in endometrial cancer through various PI3K/AKT-activating genetic alterations." (PMID 22662154, 2012). "No previous study reported on the connection between expression of those miRNAs and mTOR transcripts level in endometrial cancer." (PMID 22920721, 2012). "Our in vivo studies in 2 cell lines of xenograft mice support the in vitro findings that inhibition of the PI3K/mTOR axis has an antitumor effect in endometrial cancers." (PMID 22662154, 2012). "Robust growth suppression by NVP-BEZ235 suggests that a dual PI3K/mTOR inhibitor is a promising therapeutic for endometrial carcinomas." (PMID 22662154, 2012). "To establish a cell-based model system to understand the efficacy of mTOR inhibitors in endometrial cancer patients, we tested the growth-inhibitory properties of temsirolimus on eight endometrial cancer cell lines using in vitro proliferation assays." (PMID 22039466, 2011).
endometrial cancer (continued). "To more fully understand the therapeutic potential of mTOR inhibition in endometrial cancer, we first examined the effect of temsirolimus alone on the viability of a panel of endometrial cancer cell lines." (PMID 22039466, 2011). "While pTEN alterations are well known in endometrial cancer, signaling defects involving the downstream effector mTor, or other tumor suppressors that regulate mTor signaling, including TSC2 and LKB1, are less documented." (PMID 21931726, 2011). "mTOR inhibitors (temsirolimus, everolimus, and ridaforolimus) have been tested in phase I and II clinical trials for advanced and recurrent endometrial carcinomas with some promising clinical outcomes; however, response rates are not robust." (PMID 22039466, 2011). "It has been shown that exposure of endometrial cancer cell lines to an mTOR inhibitor increases progesterone mRNA expression and inhibits ER mRNA expression." (PMID 20148071, 2010). "Telomerase activity is regulated by Ras/PI3K/Akt pathway and mTOR inhibitor rapamycin inhibits telomerase activity in endometrial cancer cells." (PMID 20576128, 2010). "Several inhibitors of mTOR kinase have been evaluated in various solid tumours, including renal, breast, pancreatic, and endometrial cancer, and their anticancer efficacy has been shown." (PMID 19223902, 2009). "Notably, the PIK3/AKT/mTOR pathway exhibits the highest rate of alterations among solid tumors, particularly in 92% of type I and 60% of type II endometrial cancers." (PMID 41602366, 2026). "Consistent with our findings of KIF1B's inflammatory regulatory role, a previous study demonstrated that KIF5B, a kinesin family member closely related to KIF1B, regulates epithelial–mesenchymal transition through the PI3K/AKT/mTOR inflammatory pathway in endometrial cancer." (PMID 41384344, 2025). "This study aimed to detect the expression of Akt, mTOR, and Pax-2 in differing endometrial tissue/cells, together with assessment of such molecular markers for improving accuracy within endometrial cytology screening for endometrial cancer (EC)." (PMID 40357279, 2025). "Combining immune checkpoint inhibitors with therapies that target PI3K/AKT/mTOR pathway alterations, frequently found in endometrial cancers, may enhance outcomes by simultaneously addressing tumor proliferation and immune evasion mechanisms." (PMID 40072110, 2025). "MELK promotes endometrial cancer progression through activation of the mTOR signaling pathway." (PMID 39367897, 2025). "This study evaluated the safety and preliminary efficacy of an all-oral triple regimen consisting of olaparib (a PARP inhibitor), metronomic cyclophosphamide (a chemotherapy agent), and metformin (a PI3K/Akt/mTOR inhibitor) in patients with recurrent endometrial carcinomas." (PMID 41189946, 2025). "This prompted our investigation into the non-genetic mechanisms underlying PI3K–Akt–mTOR pathway activation during endometrial cancer proliferation." (PMID 39394200, 2024). "The PI3K/AKT/mTOR pathway is of paramount significance in various cancers, such as renal cancer, gastric cancer, ovarian cancer, non-small-cell lung cancer, acute myeloid leukemia, and endometrial cancer." (PMID 38584599, 2024).
endometrial cancer (continued). "The PI3K/AKT/mTOR signaling pathway is frequently altered in endometrial cancer, therefore capivasertib + AZD5991 could represent an active and potent combination in this cancer type that currently lacks effective treatments." (PMID 38456804, 2024). "Moreover, cisplatin has been reported to enhance autophagy activity through the activation of the PI3K/AKT/mTOR pathway, thus promoting endometrial carcinoma resistance to treatment." (PMID 39596186, 2024). "Therefore, the aim of our study was to assess the impact of subcellular WNT-1 and mTOR levels on the clinical course of endometrial cancer." (PMID 37176048, 2023). "First-generation mTOR inhibitors (rapalogs) that target mTOR complex 1 (mTORC1, e.g., temsirolimus and ridaforolimus), have demonstrated preliminary antitumor activity in small patient populations with recurrent endometrial cancer." (PMID 37839313, 2023). "The expression of UPF1 in endometrial cancer tissues is higher than that in adjacent tissues, which can promote the growth and progression of endometrial cancer, increase the activity of the mTOR pathway, inhibit autophagy, and promote the malignant behavior and stemness of ECSCs." (PMID 36869031, 2023). "The pathway most frequently damaged in endometrial cancer is the PI3K/AKT/mTOR pathway." (PMID 37361222, 2023). "In order to avoid resistance to endocrine therapy, we recently evaluated safety and efficacy of combining the aromatase inhibitor Anastrozole with the mTOR inhibitor Vistusertib, in 73 patients with advanced or relapsed HR+ endometrial cancer maximally treated with one line of chemotherapy." (PMID 36370117, 2023). "Since the PI3K/AKT/mTOR pathway has a high mutation rate in endometrial cancer and all of them are kinases, targeting the three major molecules of this pathway, PI3K/AKT/mTOR, has become a hot research topic for the treatment of endometrial cancer in recent years." (PMID 37644107, 2023). "Thus, the WNT/β-catenin and mTOR pathways seem to be important regulators of the growth of many types of tumors including endometrial cancer." (PMID 37176048, 2023). "Phase 2, single group assignment trial NCT01068249 evaluated the clinical benefit and the safety of the mTOR inhibitor Everolimus (10 mg/day) combined with Letrozole (2.5 mg/day) in 38 patients with recurrent endometrial cancer at 8 weeks of treatment, then every 12 weeks, up to 2 years." (PMID 37188267, 2023). "We speculated that by targeting the PI3K/AKT/mTOR pathway through inhibition of mTORC1 and 2, sapanisertib could potentiate the cytotoxic effects of paclitaxel in patients with recurrent endometrial cancer." (PMID 37839313, 2023). "PTEN has been associated with a favorable outcome in endometrial cancer, and pre-clinical data have shown that inactivating mutations in the PTEN gene may confer sensitivity to PI3K-AKT inhibitors as well as PI3K/mTOR inhibitors." (PMID 37483495, 2023). "mTOR inhibitors are therefore a potential treatment option for advanced endometrial cancer." (PMID 37839313, 2023). "Among solid tumors, endometrial cancers had the highest rate of alterations in the PI3K/AKT/mTOR pathway, with 92% of type I and 60% of type II endometrial cancers having specific alterations in this pathway, indicating that PI3K/AKT plays an important role in the pathogenesis of EC53." (PMID 37644107, 2023). "Analysis of the ribosome biogenesis factors' expression in the VICTORIA clinical trial identifies a set of preliminarily RiBi‐based markers to monitor drug activity but also to predict the response to Anastrozole and mTOR inhibitor (Vistusertib) combination therapy in advanced endometrial cancer." (PMID 36370117, 2023). "Importantly, there has been great interest in the development of novel inhibitors that target mTOR in endometrial cancer therapies." (PMID 37176048, 2023).